ALDH5A1 (aldehyde dehydrogenase 5 family member A1)
Description:
Catalyzes one step in the degradation of the inhibitory neurotransmitter gamma-aminobutyric acid (GABA).
Synonyms: SSADH; SSDH
Tractability: Small molecule: an approved drug acts on it; a structure with a bound ligand is known; it has a high-quality binding pocket; it belongs to a druggable protein family. PROTAC: ubiquitination databases record sites on it; its protein half-life has been measured; a small molecule that binds it is known.
Target class: Enzyme; Oxidoreductase
Gene: Protein-coding gene on chromosome 6 (24,494,798 to 24,537,207, forward strand). Ensembl gene ENSG00000112294.
Subcellular location: Mitochondrion
Subcellular location (Human Protein Atlas): Mitochondria
Pathways (Reactome):
Neuronal System: Degradation of GABA
Gene Ontology:
Molecular function: identical protein binding; succinate-semialdehyde dehydrogenase (NAD+) activity; oxidoreductase activity; succinate-semialdehyde dehydrogenase [NAD(P)+] activity
Biological process: central nervous system development; gamma-aminobutyrate shunt; gamma-aminobutyric acid catabolic process; glutamate metabolic process; succinate metabolic process
Cellular component: mitochondrion; mitochondrial matrix
Genetic constraint (gnomAD): Loss-of-function variants: 33 observed, 51.76 expected, observed/expected ratio (o/e) 0.64, 90% interval 0.48 to 0.85. The upper end of that interval is the gene's LOEUF score, 0.85, which puts it in group 3 of 6, group 1 being the genes least tolerant of losing a copy. Missense variants: 657 observed, 677.6 expected, observed/expected ratio (o/e) 0.97, 90% interval 0.91 to 1.03. Synonymous variants: 294 observed, 280.85 expected, observed/expected ratio (o/e) 1.05, 90% interval 0.95 to 1.15.
Gene-disease validity (ClinGen):
ClinGen rates the evidence that ALDH5A1 causes each of these diseases.
succinic semialdehyde dehydrogenase deficiency (autosomal recessive): Definitive.
Homologues: Orthologues: chimpanzee ALDH5A1 (99% identical), macaque ALDH5A1 (96% identical), rabbit ALDH5A1 (86% identical), mouse Aldh5a1 (84% identical), rat Aldh5a1 (84% identical), dog ALDH5A1 (83% identical), pig ALDH5A1 (82% identical), guinea pig ALDH5A1 (73% identical), tropical clawed frog aldh5a1 (72% identical), zebrafish aldh5a1 (65% identical), Drosophila melanogaster Ssadh (48% identical), Caenorhabditis elegans alh-7 (44% identical). Paralogues in human: ALDH1L1 (34% identical), ALDH1A3 (33% identical), ALDH1A2 (33% identical), ALDH1L2 (33% identical), ALDH1B1 (32% identical), ALDH1A1 (32% identical), ALDH2 (32% identical), ALDH9A1 (30% identical), ALDH8A1 (29% identical), ALDH6A1 (25% identical), ALDH7A1 (24% identical), ALDH16A1 (23% identical), and 5 more.
Diseases named in the same sentence as ALDH5A1 in open-access papers:
ALDH5A1 is named in the same sentence as 87 diseases in open-access papers, as found by Europe PMC text mining. Sharing a sentence is not in itself a finding about the gene and the disease. The quoted sentences say what the papers report.
epilepsy (12 papers, 2008 to 2026). A brain disorder characterized by episodes of abnormally increased neuronal discharge resulting in transient episodes of sensory or motor neurological dysfunction, or psychic dysfunction. "Succinic semialdehyde dehydrogenase deficiency (SSADHD) is a neurometabolic disorder caused by ALDH5A1 mutations presenting with autism and epilepsy." (PMID 38110041, 2024). "Our findings indicate early GABAergic alterations in Aldh5a1-/- mice, possibly exacerbated by other metabolites, which likely induce a heightened excitatory state that may predispose neural networks to epilepsy in these animals." (PMID 19040727, 2008). "Compound heterozygous variants in ALDH5A1 were found in a female patient with ASD, epilepsy, hypotonia, developmental delay, and motor coordination deficits." (PMID 40558542, 2025). "The clinical importance of ALDH5A1 rs1054899 has been confirmed in pharmacokinetic studies in Chinese patients with epilepsy treated with valproic acid (VPA) with anticonvulsant properties." (PMID 39596349, 2024). "Nowadays, ALDH5A1 is included in gene panels for epilepsy diagnostics, and many new cases were identified during the last years." (PMID 32093054, 2020).
succinic semialdehyde dehydrogenase deficiency (12 papers, 2014 to 2026). "Subsequent exome sequencing analysis identified compound heterozygous, pathogenic variants in ALDH5A1 (NM_001080.3:c.1015–2A>C and NM_001080.3:c.1597G>A (p.Gly533Arg) confirming the diagnosis of succinic semialdehyde dehydrogenase deficiency." (PMID 39011401, 2024). "A pathogenic variant in the canine ALDH5A1 gene associated with recessive SSADH deficiency, formerly known as status spongiosus in Saluki dogs (SSSD)." (PMID 32887425, 2020). "Succinic semialdehyde dehydrogenase deficiency (SSADHD) (OMIM #271980) is an inherited metabolic disorder resulting from bi‐allelic ALDH5A1 pathogenic variants." (PMID 40741980, 2025). "Succinic semialdehyde dehydrogenase deficiency (SSADHD) is a rare metabolic disorder caused by loss-of-function mutations of the ALDH5A1 gene." (PMID 38110041, 2024). "Succinic semialdehyde dehydrogenase deficiency (SSADH-D) is an autosomal recessive gamma-aminobutyric acid (GABA) metabolism disorder that can arise due to ALDH5A1 mutations, resulting in severe, progressive, untreatable neurodegeneration." (PMID 36527006, 2022). "Succinic semialdehyde dehydrogenase deficiency (SSADHD, OMIM #271980) due to biallelic variants in ALDH5A1, is one such rare neurometabolic disorder." (PMID 39011401, 2024). "Different mutations in the ALDH5A1 gene (coding for SSADH) lead to enzyme failure and cause SSADH deficiency, a rare autosomal recessive disorder of childhood and the best characterized inherited metabolic disorder of GABA catabolism." (PMID 32575506, 2020). "As an example, we will examine succinic semialdehyde dehydrogenase deficiency (SSADHD; MIM# 271980), also known as 4-Hydroxybutyric aciduria, a rare inborn error of metabolism associated with mutations in Locus ALDH5A1 (ALDH5A1; MIM# 610045)." (PMID 25420641, 2014). "There are 44 unique mutations in the ALDH5A1 gene, which occur in exons 1–10; there are no other mutations in genes other than ALDH5A1 associated with SSADH deficiency in people." (PMID 32887425, 2020).
ovarian carcinoma (9 papers, 2020 to 2025). A malignant neoplasm originating from the surface ovarian epithelium. "ALDH5A1 is positively associated with prognosis in patients with ovarian cancer, particularly in those with serous ovarian cancer." (PMID 37589009, 2023). "One clinical study shows that ALDH5A1 single-nucleotide polymorphisms were significantly associated with ovarian cancer." (PMID 34796116, 2021). "The positive association between expression of ALDH5A1 and prognosis was found in early and advanced stages of ovarian cancer patients." (PMID 32235849, 2020). "Moreover, ALDH5A1 expression was negatively associated with the prognosis of ovarian epithelial cancer." (PMID 34796116, 2021). "In grades II/III of ovarian cancer, a high mRNA level of ALDH5A1 was associated with improved OS78." (PMID 32235849, 2020). "Moreover, high ALDH5A1 levels have been associated with better OS of ovarian cancer patients." (PMID 39039535, 2024). "ALDH5A1 is downregulated in ovarian cancer, and its high expression predicts improved outcomes, serving as a favorable biomarker." (PMID 40868269, 2025). "ALDH5A1 is involved in cyclophosphamide metabolic pathways, and its expression is a predictive factor for poor prognosis in early and advanced ovarian cancer." (PMID 39596349, 2024). "In our study, elevated levels of AKR1B1 and ALDH5A1 in post-NACT treated tumors suggests alterations in proteins regulating cellular metabolism accompanies exposure of ovarian cancer cells to cytotoxic chemotherapy." (PMID 36195845, 2022). "Data analysis showed that ALDH5A1 expression was significantly reduced compared in ovarian cancer tissue to normal ovarian tissue." (PMID 34796116, 2021). "The group of Tian reported that low ALDH5A1 expression is an excellent predictive factor of poor prognosis in ovarian cancer (OC) and may play a crucial role in ovarian cancer progression." (PMID 32235849, 2020). "For example, the CRY2, ALDH5A1, and ATP6V1G2 tumor suppressor genes are involved in osteosarcoma, ovarian cancer, and glioma, respectively." (PMID 38552216, 2024). "Additionally, succinate-semialdehyde dehydrogenase, mitochondrial (ALDH5A1), which is involved in glutamate metabolism, was elevated in post-NACT treated tumors and work by Tian and colleagues identified that low expression of ALDH5A1 is associated with worse overall survival in ovarian cancer." (PMID 36195845, 2022).
developmental delay (8 papers, 2015 to 2026). "The disorder is due to bi-allelic pathogenic variants in ALDH5A1 and is usually characterized by moderate-to-severe developmental delays, hypotonia, intellectual disability, ataxia, seizures, hyperkinetic behavior, aggression, psychiatric disorders, and sleep disturbances." (PMID 39011401, 2024).
Ataxia (7 papers, 2010 to 2026). Ataxia refers to impaired coordination of voluntary muscle movement. "Interestingly, the ZIKV infection signature revealed the downregulation of ALDH5A1 and CHML, genes implicated in neurological (cognitive impairment, expressive language deficit, and mild ataxia) and ophthalmic (choroideremia) disorders, respectively." (PMID 30046058, 2018). "From the figures, it can be seen that differences related to ataxia are significant, and genes with strong correlations are VLDLR, ALDH5A1, and CACNA1C, and strong correlations means these correlations between gene variants and ataxia (or phenotype)." (PMID 31291898, 2019).
glioma (5 papers, 2012 to 2024). A benign or malignant brain and spinal cord tumor that arises from glial cells (astrocytes, oligodendrocytes, ependymal cells). "We also studied the grade-wise expression of ALDH5A1 in the glioma datasets: CGGA, Rembrandt, and Gravendeel." (PMID 39039535, 2024). "Through univariate Cox analysis, they also identified that ALDH5A1 was one of the 5 protective genes in glioma that is involved the GO biological process ‘nervous system development’." (PMID 39039535, 2024). "For this, we studied the HPA where immunohistochemical analysis of ALDH5A1 was performed in a cohort of 9 glioma patients." (PMID 39039535, 2024). "SSADH downregulation by siRNA targeting of ALDH5A1 mRNA caused accumulation of GHB not only in stem-like cells of adult GBM but also in stem-like cells of infant DIPG, a form of high-grade glioma with a poor prognosis." (PMID 28032215, 2017). "Meta-analysis of normalized gene expression profiles in the GeneSapiens “body-wide” microarray database reveals that the median level of ALDH5A1 expression is significantly higher in certain cancers (particularly glioma and some leukemias and lymphomas)." (PMID 23236365, 2012). "Interestingly, we found that high ALDH5A1 showed a significant correlation to better survival in multiple glioma patient datasets." (PMID 39039535, 2024). "This suggested that ALDH5A1 had relatively low protein expression in glioma patient samples." (PMID 39039535, 2024). "Although there are some controversial observations regarding ALDH5A1 expression in glioma, our analysis of multiple patient datasets suggest that ALDH5A1 is significantly downregulated in GBM compared to the normal brain, and its low levels are associated with poor prognosis." (PMID 39039535, 2024). "Interestingly, we also observed that ALDH5A1 expression is elevated and miR-210 levels are downregulated in IDH-mutant glioma as compared to its wild-type form." (PMID 39039535, 2024). "Analysis of the TCGA dataset showed that ALDH16A1, ALDH3B1, ALDH1A3, ALDH3A1, ALDH7A1 were significantly increased in IDH wildtype gliomas, while ALDH2, ALDH6A1, ALDH5A1, ALDH1A1, ALDH1L2, ALDH18A1, ALDH1B1 expression were higher in IDH mutant gliomas than IDH wildtype gliomas." (PMID 35116021, 2021). "In the LGG cohort from the TCGA dataset, ALDHs including ALDH2, ALDH6A1, ALDH5A1, ALDH9A1, ALDH1A1 were upregulated in WHO grade II gliomas while the increased expression of ALDH16A1, ALDH3B1, ALDH3A2, ALDH1A2, ALDH3A1 was found in WHO III grade gliomas." (PMID 35116021, 2021).
glioblastoma (4 papers, 2017 to 2024). The most malignant astrocytic tumor (WHO grade IV). "By exploring the IVY Glioblastoma Project (IVY-GAP) dataset, we observed that ALDH5A1 mRNA expression is significantly downregulated in the hypoxic pseudopalisades of GBM patients, when compared to the leading edge and cellular tumor." (PMID 39039535, 2024). "Transient overexpression of cDNA constructs harboring wild-type (WT) ALDH5A1 gene, triple mutant (TM, c.106G > C, c.538C > T and c.545C > T, CTT), or the empty pcDNA3.1 vector (control) was performed in U87 glioblastoma cells." (PMID 32575506, 2020).
serous ovarian cancer (4 papers, 2019 to 2025). "Although the role of ALDH5A1 in HCC is unclear at present, its downregulation in high-grade serous ovarian cancer (HGSOC) is associated with the presence of an EMT gene signature and poor prognosis, implying a role in the migration and invasion of HGSOC." (PMID 35898502, 2022).
papillary thyroid carcinoma (3 papers, 2023 to 2024). "More recently, the analysis results from the TCGA database show that ALDH5A1 is an excellent prognostic factor in patients with primary papillary thyroid cancer (PTC), manifesting that the high expression of ALDH5A1 predicts a worse prognosis." (PMID 36694633, 2023). "Additionally, the oncogenes, ALDH5A1 and NAP1L3, exerted effects in papillary thyroid carcinoma and hepatocellular carcinoma, respectively." (PMID 38552216, 2024).
bipolar disorder (2 papers, 2020 to 2024). A disorder of the brain that causes unusual shifts in mood, energy, activity levels and the ability to carry out day-to-day tasks. "Valproic acid was originally developed to treat episodes of bipolar disorder and seizures (nervous system diseases) by hitting the mitochondrial enzymes succinate-semialdehyde dehydrogenase (ALDH5A1) and 4-aminobutyrate aminotransferase (ABAT)." (PMID 32419905, 2020).
Encephalopathy (2 papers, 2008 to 2020). Encephalopathy is a term that means brain disease, damage, or malfunction. "The human phenotype is that of nonprogressive encephalopathy with prominent bilateral discoloration of the globi pallidi and variable seizures, the latter displayed prominently in Aldh5a1-/- mice with lethal convulsions." (PMID 19040727, 2008).
renal cell carcinoma (2 papers, 2012 to 2024). "Very little is known about ALDH5A1 with regard to cancer, beyond an observation in renal cell carcinoma cells that it is regulated by hepatocyte nuclear factor 4alpha." (PMID 23236365, 2012).
autoimmune disease (1 paper, 2024). A disorder resulting from loss of function or tissue destruction of an organ or multiple organs, arising from humoral or cellular immune responses of the individual to their own tissue constituents. "Plasma proteins with positive correlation with AS in this study were TNF, FKBPL, AGER, and ALDH5A1.TNF is a crucial cytokine playing a key role in the human immune response, involving various inflammatory and autoimmune diseases in their onset and development." (PMID 38566994, 2024).
brain-tumor (1 paper, 2024). "To further understand the clinical relevance of ALDH5A1 in GBM, we downloaded GBM patient survival data along with ALDH5A1 expression from various brain-tumor datasets using the GlioVis tool." (PMID 39039535, 2024). "For this, we downloaded ALDH5A1 mRNA expression data from various brain-tumor datasets using the GlioVis web-tool." (PMID 39039535, 2024).
breast carcinoma (1 paper, 2012). "From among the group of differentially expressed gene products in the DCIS models that are involved in glutamate metabolism, we chose to focus on ALDH5A1 due to its novelty in the context of breast cancer and status as an established druggable target." (PMID 23236365, 2012). "Second, ALDH5A1 represented a novel transcript that had not previously been associated with breast cancer." (PMID 23236365, 2012). "Its antitumor activity has been previously reported in both in vitro and in xenograft studies of breast cancer cell lines, but the possibility that this activity could be due to inhibition of the ALDH5A1 isoform was not previously considered." (PMID 23236365, 2012). "Notably, there are outliers of breast cancers classified as ductal and classified as not-otherwise-specified (which would include DCIS and IDC, respectively) in which ALDH5A1 is increased in expression." (PMID 23236365, 2012).
breast ductal carcinoma in situ (1 paper, 2023). "RNA sequencing analysis of human breast ductal carcinoma in situ (DCIS) cells demonstrates that ALDH5A1 is overexpressed at both the mRNA and protein levels." (PMID 36694633, 2023).
colitis (1 paper, 2024). Inflammation of the colon. "The results demonstrated a downregulation of mRNA and protein expression levels of PDK2, CHDH, and ALDH5A1 in colitis cells and tissues, which aligns with our previous bioinformatic analysis." (PMID 38376420, 2024). "Collectively, our findings indicate that the influence of PDK2, CHDH, and ALDH5A1 on the advancement of DSS-induced colitis in mice is potentially mediated through the regulation of macrophage infiltration." (PMID 38376420, 2024). "Additionally, the expression levels of PDK2, CHDH, and ALDH5A1 were lower in colitis tissues, which aligns with the results obtained from the bioinformatic analysis." (PMID 38376420, 2024). "Western blotting analysis demonstrated a reduction in the protein expression levels of ALDH5A1, PDK2, and CHDH in the colitis lesions of mice administered with DSS." (PMID 38376420, 2024). "And the results also demonstrated that CD86 exhibited higher expression in mouse colitis lesions, whereas PDK2, CHDH, and ALDH5A1 displayed lower expression in these lesions." (PMID 38376420, 2024). "Ultimately, the verification of the expression of signature genes (ALDH5A1, CHDH, and PDK2) and their co-expression with M1 macrophages (CD86) was accomplished through the construction of inflammatory cell and colitis models." (PMID 38376420, 2024).
Dystonia (1 paper, 2024). An abnormally increased muscular tone that causes fixed abnormal postures. "Our analysis also uncovered pathogenic or likely pathogenic variants in uncommonly dystonia-associated genes (PCCB, CACNA1A, ALDH5A1, PRKN) in four families where dystonia has been rarely observed in the spectrum of the clinical characteristics so far." (PMID 38458754, 2024). "Pathogenic or likely pathogenic variants were found in four families in genes that are not commonly associated with dystonia (PCCB, CACNA1A, ALDH5A1 and PRKN)." (PMID 38458754, 2024).
epileptic syndromes (1 paper, 2017). "Using a standard array for characterization of genes under/over-expressed in epileptic syndromes, we identified six genes dysregulated at least 4-fold in aldh5a1-/- NSC cultures relative to wild-type." (PMID 29053743, 2017).
liver cancer (1 paper, 2022). An epithelial or non-epithelial malignant neoplasm that arises from the liver. "The results showed that ALDH1A1, ALDH1L1, ALDH1L2, ALDH3A1, ALDH3A2, ALDH5A1, and ALDH8A1 gene expressions were significantly different between liver cancer and normal tissues." (PMID 34928471, 2022).
lung carcinoma (1 paper, 2021). "Because LMD samples from pediatric patient CSF were not readily available, we analyzed ABAT and ALDH5A1 expression in LMD samples from the CSF of patients with breast and lung cancer as a surrogate." (PMID 34192534, 2021).